STIM2 (stromal interaction molecule 2)
Description:
Plays a role in mediating store-operated Ca(2+) entry (SOCE), a Ca(2+) influx following depletion of intracellular Ca(2+) stores. Functions as a highly sensitive Ca(2+) sensor in the endoplasmic reticulum which activates both store-operated and store-independent Ca(2+)-influx. Regulates basal cytosolic and endoplasmic reticulum Ca(2+) concentrations. Upon mild variations of the endoplasmic reticulum Ca(2+) concentration, translocates from the endoplasmic reticulum to the plasma membrane where it probably activates the Ca(2+) release-activated Ca(2+) (CRAC) channels ORAI1, ORAI2 and ORAI3. May inhibit STIM1-mediated Ca(2+) influx.
Tractability: Antibody: its Gene Ontology location is reachable by antibodies, with high confidence; UniProt predicts a signal peptide or a membrane-spanning region. PROTAC: ubiquitination databases record sites on it; its protein half-life has been measured; a small molecule that binds it is known.
Gene: Protein-coding gene on chromosome 4 (26,857,601 to 27,025,381, forward strand). Ensembl gene ENSG00000109689.
Subcellular location: Endoplasmic reticulum membrane
Gene Ontology:
Molecular function: calcium channel regulator activity; calcium ion binding; protein binding; store-operated calcium channel activity
Biological process: activation of store-operated calcium channel activity; intracellular calcium ion homeostasis; positive regulation of calcium ion transport; store-operated calcium entry; calcium ion transmembrane transport; regulation of calcium ion transport
Cellular component: endoplasmic reticulum; plasma membrane; endoplasmic reticulum membrane
Genetic constraint (gnomAD): Loss-of-function variants: 23 observed, 64.42 expected, observed/expected ratio (o/e) 0.36, 90% interval 0.26 to 0.51. The upper end of that interval is the gene's LOEUF score, 0.51, which puts it in group 2 of 6, group 1 being the genes least tolerant of losing a copy. Missense variants: 763 observed, 788 expected, observed/expected ratio (o/e) 0.97, 90% interval 0.91 to 1.03. Synonymous variants: 320 observed, 293.2 expected, observed/expected ratio (o/e) 1.09, 90% interval 1 to 1.2.
Homologues: Orthologues: chimpanzee STIM2 (99% identical), macaque STIM2 (99% identical), rabbit STIM2 (95% identical), mouse Stim2 (94% identical), rat Stim2 (94% identical), guinea pig STIM2 (91% identical), tropical clawed frog stim2 (72% identical), pig STIM2 (69% identical), zebrafish stim2b (60% identical), zebrafish stim2a (49% identical), Drosophila melanogaster Stim (27% identical), Caenorhabditis elegans stim-1 (19% identical). Paralogues in human: STIM1 (44% identical).
Diseases named in the same sentence as STIM2 in open-access papers:
STIM2 is named in the same sentence as 64 diseases in open-access papers, as found by Europe PMC text mining. Sharing a sentence is not in itself a finding about the gene and the disease. The quoted sentences say what the papers report.
breast carcinoma (17 papers, 2013 to 2025). "STIM2 is relevant in leukaemia, while Orai3 is associated with the migration of breast cancer cells and is linked to pancreatic tumour growth." (PMID 35681544, 2022). "Taken together, these results suggest that loss of STIM2 inhibits EMT and gain of STIM2 enhances EMT in breast cancer cells." (PMID 31464639, 2019). "Because we found an association between elevated STIM2 expression and enhanced cellular migration, we chose an epithelial-like breast cancer cell line with low metastatic potential, MCF7, for further comparison with the metastatic MDA-MB-231 cell line." (PMID 31464639, 2019). "An increase in STIM1/STIM2 gene expression ratio has been associated with reduced survival in breast cancer patients." (PMID 23594099, 2013). "STIM2 was also implicated in breast cancer metastasis through supporting EMT." (PMID 34069353, 2021). "Deletion of STIM1 and STIM2, either individually or together, in the isogenic lung derivative and highly metastatic breast cancer cell line LM2-4 revealed that the observed phenomena were not unique to MDA-MB-231 cells." (PMID 40719699, 2025). "In ER+ breast cancer cells, SOCE is mediated exclusively by Orai3 and STIM1/STIM2, whereas in ER- breast cancer cells, the canonical CRAC channel consists of STIM1/Orai1, which is sufficient to trigger SOCE." (PMID 36612099, 2022). "Consistently, overexpression of STIM1 and STIM2 in the less aggressive MCF-7 breast cancer cells enhances cell migration and invasiveness." (PMID 34069353, 2021). "From the functional point of view, SOCE in MCF7 is mediated by STIM1, STIM2, and Orai3, in contrast to other breast cancer subtypes, such as TNBC cells, where SOCE is entirely dependent on STIM1 and Orai1." (PMID 34439314, 2021). "We also examined the expression of STIM2 and STIM1 in a panel of breast cancer cell lines and found a higher level of STIM2 in two mesenchymal-like cell lines (MDA-MB-231, BT-549) than in three epithelial-like cell lines (T-47D, BT-474, and MCF7)." (PMID 31464639, 2019). "Our results demonstrate for the first time that STIM2 is a master regulator of NFAT1 in breast cancer." (PMID 31464639, 2019). "Knockdown of STIM2 inhibited the motility of breast cancer cells by inhibiting EMT via specific suppression of NFAT1 and inhibited mammary tumor metastasis in mice." (PMID 31464639, 2019). "In the current study, we provided evidence showing the activation of an NFAT1–TGF-β1 axis in breast cancer cells along with its upstream driver STIM2." (PMID 31464639, 2019). "It has been demonstrated that SOCE in estrogen receptor (ER)-positive breast cancer cells is mediated by Orai3 and STIM2/STIM1, whereas SOCE in ER-negative breast cancer cells mostly depends on the canonical Orai1/STIM1 pathway." (PMID 31252656, 2019). "The nuclear and cytoplasmic staining intensity of STIM2 was significantly stronger in breast cancer samples than in normal mammary epithelial tissue samples." (PMID 31464639, 2019). "STIM1 and STIM2 are critical regulators of breast cancer cell migration." (PMID 40719699, 2025). "STIM2 knockdown inhibited breast cancer cell migration and metastasis in xenograft models." (PMID 34069353, 2021). "This suggests that the STIM1/STIM2 expression ratio may represent a good prognostic marker for breast cancer." (PMID 32825277, 2020). "Our findings suggest that STIM1 and STIM2 differentially regulate intracellular Ca2+ via different downstream signaling pathways and indicate that STIM2 plays an important but previously unappreciated role in promoting breast cancer metastasis." (PMID 31464639, 2019). "As the central node of this axis, STIM2 activation may serve not only as a prognostic factor to predict clinical outcomes for breast cancer patients, but also as a potential therapeutic target." (PMID 31464639, 2019).
breast carcinoma (continued). "However, STIM2 promotes breast cancer metastasis via regulating the expression of the transcription factor nuclear factor of activated T cells 1 (NFAT1) and its translocation to the TGF-β1 promoter, leading to upregulated expression and secretion of TGF-β1." (PMID 31464639, 2019). "Our observation of poorer RFS in some breast cancer subtypes with high ORAI3 and low ORAI1 levels, is reflective of the association between the ORAI1 activators STIM1/STIM2 in basal breast cancers, where high STIM1/low STIM2 was associated with poorer survival." (PMID 30754719, 2019). "Intriguingly, STIM2 protein level—evaluated as a combination of IHC staining intensity and the percentage of positively stained cells—was significantly higher in samples of breast cancer lymph node metastases than in primary breast tumor samples." (PMID 31464639, 2019). "We then investigated whether STIM2 influences EMT in breast cancer cells by determining expression levels of two markers of EMT, E-cadherin and vimentin." (PMID 31464639, 2019). "A microarray study of breast tumor revealed that the high STIM1/STIM2 expression profiles accompanied by augmented SOCE were correlated with the breast cancer subtype with the poorest prognosis, suggesting the clinical significance of STIM1/STIM2 ratio in breast cancer." (PMID 31252656, 2019). "We hypothesized that STIM2 regulates epithelial-mesenchymal transition (EMT) to promote breast cancer metastasis." (PMID 31464639, 2019). "In addition, silencing of STIM2 in breast cancer cells inhibited, whereas overexpression of STIM2 enhanced, the migration of breast cancer cells." (PMID 31464639, 2019). "Thus, we have uncovered a novel mechanism by which STIM2 distinctively modulates EMT to promote breast cancer cell motility and tumor metastasis." (PMID 31464639, 2019). "Moreover, STIM2 and Orai2/3 are relevant to cancerous processes, whereby Orai2 was, for instance, reported to promote migration and metastasis in gastric cancer and is important for cell cycle progression of breast cancer cells." (PMID 35681544, 2022). "Agonist-evoked Ca2+ signals through the activation of Orai1 also fine tune breast cancer cell functions as described in triple negative breast cancer cells where progesterone attenuates cell proliferation by a mechanism involving Ca2+ entry mediated by STIM2, Orai1, and TRPC1." (PMID 33916304, 2021). "Although both STIM1 and STIM2 sense calcium release, leading to influx of extracellular calcium, our results demonstrate that gain or loss of STIM1 alone has minimal effect on EMT, whereas gain or loss of STIM2 has a substantial impact on EMT in breast cancer cells." (PMID 31464639, 2019). "Thus, we hypothesized that STIM2 regulates EMT in breast cancer cells by influencing the intracellular Ca2+ level." (PMID 31464639, 2019). "This can be achieved by future studies utilizing techniques including siRNA to perform a specific knockdown of STIM1 and STIM2, which will enable researchers to identify the specific roles of these proteins in the TLR4-induced signaling of breast cancer cells." (PMID 37371732, 2023). "Although the focus of our research was to investigate the influence of SOCE on the LPS-mediated signaling in breast cancer cells, we also examined the effect of LPS on the expression of the SOCE-related genes STIM1 and STIM2." (PMID 37371732, 2023). "Gene chip microarray of 295 breast cancer patients revealed a high STIM1 and low STIM2 expression in basal-like tumours that have a particularly poor prognosis and few treatment options." (PMID 32825277, 2020). "This study reveals several new aspects of the role of STIM family members, particularly STIM2, in EMT and breast cancer metastasis." (PMID 31464639, 2019). "In this study, we aimed to determine STIM2’s role in regulating EMT and promoting breast cancer metastasis by identifying its specific downstream targets." (PMID 31464639, 2019).
breast carcinoma (continued). "The basal subtype breast cancers are also more likely to have higher mRNA levels of the canonical ORAI channel activator STIM1, and lower levels of its related isoform STIM2." (PMID 30034631, 2018). "Consistent with the in vitro model, there was no consistent change in Orai1, STIM1, or STIM2 transcript levels in CAFs and NFs in paired breast cancer patient samples." (PMID 34208665, 2021). "Moreover, microarray analysis data show that, the basal-breast cancer, a breast cancer subtype with a very dismal prognosis, is correlated with an altered relationship between the ORAI1 activators STIM1 and STIM2, characterized by high STIM1/STIM2 ratios." (PMID 32733237, 2020). "Although STIM1 has been reported to affect focal adhesion turnover and rearrangement in several types of cancer cells, the role of STIM2 in regulating EMT and metastasis in breast cancer is unknown." (PMID 31464639, 2019). "Taken together, our results demonstrated that STIM2 specifically regulates NFAT1, which in turn regulates the expression and secretion of TGF-β1 to promote EMT in vitro and in vivo, leading to metastasis of breast cancer." (PMID 31464639, 2019). "Motiani and coworkers confirmed that SOCE in triple negative MDA-MB-231 breast cancer cells is entirely dependent on STIM1 and Orai1, while in MCF7, SOCE is mediated by STIM1, STIM2 and Orai3 (overexpressed in this cell line), thus reporting important phenotypic differences between both cell lines." (PMID 30558192, 2018). "Thus, in triple negative breast cancer cells, such as MDA-MB-231 cells, SOCE has been reported to be strongly dependent on STIM1 and Orai1, with TRPC6 playing a relevant role in the surface expression of Orai1, while in luminal breast cancer cells SOCE is mostly mediated by STIM1, STIM2, and Orai3." (PMID 33916304, 2021). "Another study, based on the microarray data analyses of 295 breast cancer patients, also showed that transcriptionally-defined basal-like tumors, which have a poor prognosis and lack of effective therapies, are characterized by high STIM1 and low STIM2 mRNA expressions." (PMID 23594099, 2013). "Therefore, STIM2 and STIM1 may regulate different signaling pathways (SOCE and non-SOCE), with STIM2 playing a more important role in regulating breast cancer cell motility and promoting metastasis." (PMID 31464639, 2019). "Because knockdown or overexpression of STIM1 did not affect the expression of EMT markers in breast cancer cells, we conclude that STIM2, but not STIM1, regulates EMT in breast cancer cells." (PMID 31464639, 2019). "Second, we found that STIM2, but not STIM1, promotes EMT in metastatic breast cancer cells." (PMID 31464639, 2019).
melanoma (13 papers, 2013 to 2024). A malignant, usually aggressive tumor composed of atypical, neoplastic melanocytes. "It was reported that C313 in STIM2 can be oxidated and thereby inhibit its oligomerization in melanoma cells." (PMID 39272139, 2024). "Melanoma cells express high levels of Orai1 and STIM2, both of which control store-operated Ca2+ entry." (PMID 39764412, 2024). "A recent publication by Gibhardt and collaborators addressed the regulatory mechanisms by which STIM2 is regulated by oxidative stress in melanoma cells." (PMID 36614330, 2023). "Except for melanoma, STIM2 overexpression in cancer cells and their invasiveness are inversely correlated." (PMID 34572262, 2021). "In the same vein, STIM2 overexpression was detected in human melanoma, where STIM2 siRNA treatment produced enhanced proliferation." (PMID 32733237, 2020). "Elevated STIM2 expression levels have been found in different cancer types, colorectal cancer, human melanoma and glioblastoma multiform tumors." (PMID 32733237, 2020). "In human melanoma, STIM2 and Orai1 were highly expressed in primary human melanomas and elevated in the invasive rim of the lymph node metastatic tumors." (PMID 31252656, 2019). "The overexpression of STIM2 inhibits cell proliferation and tumor growth in colorectal cancers in vivo but promotes cell migration in primary melanoma in vivo, implicating the contribution of STIM2 signaling at different stages of tumor progression." (PMID 30935064, 2019). "We found that STIM1 and STIM2 in T cells are required to curtail tumour growth in animal models of melanoma and adenocarcinoma." (PMID 23922331, 2013). "Melanoma cell growth and invasion are inversely controlled by Orai1 and STIM2 in a dynamic manner." (PMID 39764412, 2024). "Similarly, STIM2 overexpression favors melanoma cell migration and invasive, which can be prohibited due to the C313 being sulfonylated by reactive oxygen species (ROS) that block STIM2 oligomerization and gating ORAI." (PMID 39272139, 2024). "Interestingly, STIM2 upregulation in melanoma cells has been known to contribute to antiproliferative but invasive phenotype." (PMID 34572262, 2021). "Furthermore, based on in vivo experiments, STIM2 is assumed to play a role in tumor invasion and metastasis of melanoma." (PMID 33333945, 2020). "A pro-migratory role of STIM2/Orai1-mediated SOCE has also been reported in melanoma." (PMID 31252656, 2019). "Furthermore, the high Orai1 and STIM2 expression found in melanoma biopsies at the rim of invading tumors are linking their possible role in tumor invasion and/or metastasis in vivo." (PMID 30935064, 2019). "However, the role of STIM2 in melanoma cells has remained less understood." (PMID 33333945, 2020). "High levels of STIM1, STIM2 and SOCE were also documented in metastatic melanoma as compared to primary melanoma and knockdown of Orai1 and/or STIM2 reduced melanoma cell migration and invasiveness." (PMID 34069353, 2021). "In fact, STIM2, together with ORAI1, promotes growth and invasion of melanoma cells." (PMID 36614330, 2023). "In contrast, STIM2, Orai2 and Orai3 expression was undetectable or barely detectable in the melanoma cell lines (data not shown)." (PMID 24586666, 2014). "Using conditional knock out mice lacking STIM1 and its homologue STIM2, we find that SOCE in CD8+ T cells is required to prevent the engraftment of melanoma and colon carcinoma cells and to control tumour growth." (PMID 23922331, 2013). "As a consequence, CTL lacking both Stim1 and Stim2 genes and therefore CRAC channel function failed to control the growth of melanoma and colon carcinoma cells and to prevent tumour engraftment." (PMID 23922331, 2013).
Alzheimer disease (8 papers, 2014 to 2022). A progressive, neurodegenerative disease characterized by loss of function and death of nerve cells in several areas of the brain leading to loss of cognitive function such as memory and language. "Although possessing higher expression level in the cortex and hippocampus, the role of STIM2 in the disease progression of Alzheimer’s disease has been less studied." (PMID 35821821, 2022). "STIM2 knockdown was reported to rescue the amplitude of SOCE and attenuate intracellular Ca2+ load in a cellular model of Alzheimer’s disease that was caused by the expression of mutant presenilin 1 M146V." (PMID 30455632, 2018). "In addition, the downregulation of STIM2 proteins was observed in cells from Alzheimer’s disease (AD) patients and in AD mouse models." (PMID 34948414, 2021). "Moreover, it has been observed that STIM2 hyperexpression as well as the pharmacological activation of nSOC in the hippocampus is able to protect mushroom spines in different models of Alzheimer disease pathology." (PMID 34948414, 2021). "Systemic ablation of the Stim2 gene protects against hypoxic neuronal cell death and reduced levels of STIM2 in a presenilin-1 mouse model of Alzheimer's disease accounts for a decrease in the fraction of mature (mushroom) dendritic spines in hippocampal neurons." (PMID 26236206, 2015). "In the brain there are two species of STIM, STIM1, which has been shown recently to link to mGluRs and play a critical role in cerebellar neurons, and STIM2 which appears to regulate influx of calcium in forebrain neurons, and be related to Alzheimer’s disease (AD) (below)." (PMID 25071469, 2014). "There is evidence that overexpression of both STIM2 and Orai1 increased neuronal Ca2+ level; however, no sign of neurodegeneration was observed, suggesting a dissociation of SOCE machinery with Alzheimer’s disease progression as determined by amyloidogenesis and immunohistochemistry." (PMID 35821821, 2022).